SRSF2 (serine and arginine rich splicing factor 2)
Diseases named in the same sentence as SRSF2 in open-access papers (continued):
Sharing a sentence is not in itself a finding about the gene and the disease.
gastric cancer (8 papers, 2016 to 2025). A primary or metastatic malignant neoplasm involving the stomach. "The experiments revealed a reduced expression of SRSF1 and SRSF2 in pancreatic, kidney, colorectal, and stomach cancer cell lines as well as in cancer tissues — SRSF2 was downregulated in stomach tumors, while SRSF1 was reduced in all types of tested tumors." (PMID 27019673, 2016). "Besides, miR-183-5p and miR-200c-3p in renal cancer as well as miR-193a-3p in gastric cancer have been demonstrated to target the SRSF2 (SC35) 3′-UTR mRNA, affecting the maturation of several pre-mRNAs involved in the apoptosis." (PMID 32596243, 2020). "Similarly, inhibition of Clk1 using TG003 and Clk1 siRNA resulted in a decreased cell viability, proliferation, invasion and migration as well as modulation in the phosphorylation of SRSF2, which validated the use of Clk1 as a potential target for gastric cancer treatment." (PMID 37658940, 2023). "Acetylation of SRSF2 by LLPS upregulates YTHDF1 expression and promotes gastric cancer cell proliferation and migration." (PMID 40211955, 2025). "In gastric cancer, NAT10 engages with the splicing factor serine/arginine-rich splicing factor 2 (SRSF2), instigating its acetylation and subsequent stabilization." (PMID 40588654, 2025). "The acetylated SRSF2 subsequently binds to YTHDF1, enhancing its expression and thereby promoting the proliferation and migration of gastric cancer cells." (PMID 40211955, 2025). "In gastric cancer, NAT10-mediated SRSF2 stabilization induces exon skipping in YTHDF1 pre-mRNA, creating a truncated m6 A reader isoform that promotes tumor progression." (PMID 40588654, 2025). "To evaluate their clinical relevance of Drosha, SRSF2, ABHD16A and miR-4646-5p, we tested their expression levels in 60 samples of gastric cancer patients." (PMID 33875796, 2021). "Additionally, upregulation of miR-193a-3p can modulate serine/arginine-rich splicing factor 2 (SRSF2) expression, inhibit mitochondrial-dependent cellular apoptosis, and confer resistance to cisplatin in gastric cancer cells." (PMID 40078288, 2025).
uveal melanoma (8 papers, 2019 to 2025). A melanoma derived from melanocytes of the uveal tract. "This suggests that the R625 missense SF3B1 mutations and SRSF2 mutations in UM are different compared to the spliceosome gene mutations in hematological cancers, and probably target a different, as yet unknown, set of genes involved in uveal melanoma etiology." (PMID 31426461, 2019). "The first mutation set encompasses the eight UM driver genes according to the TCGA study, divided into “uveal melanoma initiating mutations” (CYSLTR2, GNA11, GNAQ and PLCB4) and “second hit mutations with prognostic impact” (BAP1, EIF1AX, SF3B1 and SRSF2)." (PMID 39858540, 2025).
colorectal cancer (7 papers, 2018 to 2024). A primary or metastatic malignant neoplasm that affects the colon or rectum. "In colorectal cancer, the tumor promoter circPLCE1 directly binds to SRSF2, resulting in the repression of SRSF2-dependent PLCE1 pre-RNA splicing, which leads to tumor progression." (PMID 38778254, 2024). "Overexpression of SRSF2 promoted proliferation in colorectal cancer cells, while inhibition of its expression prevented tumor formation." (PMID 39286028, 2024). "Herein, we found SRSF2 to be highly expressed in human colorectal cancer (CRC) samples compared with normal tissues." (PMID 36623729, 2023). "Together, these observations strongly indicate that SRSF2 is increased in human colorectal cancer samples and predicted as a potential biomarker for CRC patients." (PMID 36623729, 2023). "Here, we report a novel circular RNA circPLCE1 (hsa_circ_0019230) that facilitates the malignant progression of colorectal cancer (CRC) by repressing serine/arginine‐rich splicing factor 2 (SRSF2)‐dependent phospholipase C epsilon 1 (PLCE1) pre‐RNA splicing." (PMID 34173324, 2021). "The individual with the SRSF2 p.P95L variant is the same patient with the TET2 p.I1873T variant and mast cell leukaemia/colorectal cancer." (PMID 29641532, 2018). "Collectively, our findings identify that SRSF2 dysregulates colorectal carcinoma proliferation at the molecular level of splicing regulation and reveal potential splicing targets in CRC patients." (PMID 36623729, 2023). "Aberrant expression of serine/arginine-rich splicing factor 2 (SRSF2) can lead to tumorigenesis, but its molecular mechanism in colorectal cancer is currently unknown." (PMID 36623729, 2023). "Interestingly, we found that two enriched motifs, SRSF2 and U2AF2, were previously reported to be highly involved in AML progression through aberrant splicing regulation and another motif, PTBP1, was shown to play an important role in breast and colorectal cancers." (PMID 29665865, 2018).
lung carcinoma (7 papers, 2012 to 2024). "We recently reported that SRSF2 controls the splicing of VEGFR1 in lung cancer cells upon VEGF165 stimulation." (PMID 34433435, 2021). "As a whole, these data demonstrated that a VEGF165/SOX2/SRSF2 network controls VEGFR1 pre-mRNA splicing towards sVEGFR1-i13 expression in lung cancer cells treated with anti-angiogenic therapies." (PMID 30674935, 2019). "For HER1/EGFR, we showed a down-regulation of one of the transcripts (last exon > e20) in SRSF2-over-expressing H358 lung cancer cells in comparison to H358 control cells." (PMID 24428911, 2014). "BE developed the SRSF2-over-expressing lung cancer cells, and performed the western blotting experiments." (PMID 24428911, 2014). "As a proof of concept, we demonstrated the ability of such a chip to detect the effects of over-expressed SRSF2 RNA binding protein on the structure and abundance of mRNA products in H358 lung cancer cells conditionally over-expressing SRSF2." (PMID 24428911, 2014). "To analyze the gene expression changes triggered by over-expression of SRSF2 in H358 lung cancer cells, we performed an analysis using 44 k AgilentTM microarrays." (PMID 24428911, 2014). "Major splicing changes were observed, including in HER1/EGFR pre-mRNA, which were also seen in human lung cancer samples over-expressing the SRSF2 protein." (PMID 24428911, 2014). "The 15 k custom microarray predicted multiple exon skipping in the 3′ region of HER1/EGFR in SRSF2-over-expressing H358 lung cancer cells, which was confirmed by quantitative RT-PCR." (PMID 24428911, 2014). "Overall, our results support the idea that variations in expression, localization and/or activity (through phosphorylation) of SRSF1 and SRSF2 proteins take place during lung cancer progression." (PMID 23071587, 2012). "We recently demonstrated that SRSF2 is involved in cisplatin-mediated apoptosis of human lung carcinoma cell lines." (PMID 23071587, 2012). "Using patient-derived material, we observed that strong SRSF2 over-expression in NSCLC is associated with splicing alterations of the HER1/EGFR and VEGFA transcripts, as predicted from the results in the SRSF2-over-expressing H358 lung cancer cell line." (PMID 24428911, 2014). "Interestingly, we recently demonstrated that phosphorylation of SRSF2 (former SC35) by SRPK2 is involved in cisplatin-mediated apoptosis of human lung carcinoma cell lines." (PMID 23071587, 2012). "As an example, we previously reported the upregulation of SRSF1, SRSF2, and SRPK1 proteins in lung cancer patients." (PMID 34433435, 2021). "Interestingly, the three NSCLC samples with the highest SRSF2 and phospho-SRSF2 scores all displayed a drop in the HER1/EGFR "last exon > e20" transcript, as determined by quantitative RT-PCR, similarly to what occurred in lung cancer cells." (PMID 24428911, 2014). "Notably, SRSF2 over-expression modified HER1/EGFR and VEGFA expression in H358 lung cancer cells." (PMID 24428911, 2014).
colon cancer (6 papers, 2014 to 2025). "We further revealed the function of SLMAP-L and CETN3-S splice variants and their regulator SRSF2 in proliferation of colon cancer cells." (PMID 36623729, 2023). "The knockdown of SRSF2 and its cancer-associated splicing events SLMAP-L or CETN3-S decreased malignant proliferation of colon cancer cells." (PMID 36623729, 2023). "Taken together, these in vitro and in vivo data confirmed that SRSF2 promoted proliferation in colon cancer cells." (PMID 36623729, 2023). "Overall, SRSF2 is involved in all common modes of AS, among which cassette exons are the most frequent targets of SRSF2 regulation in colon cancer cells." (PMID 36623729, 2023). "Cell Counting Kit-8 assays verified that SRSF2 knockdown severely inhibited the growth of colon cancer cells." (PMID 36623729, 2023). "Knockdown of SRSF2, its splicing targets SLMAP-L, or CETN3-S caused colon cancer cells to arrest in G1 phase of the cell cycle." (PMID 36623729, 2023). "SLMAP-L, CETN3-S, and their splicing regulator SRSF2 stimulated the proliferation of colon cancer cell." (PMID 36623729, 2023). "Restoration of SLMAP-L or CETN3-S partially abolishes the antiproliferation effects of SRSF2 knockdown via mediating cell cycle progression in colon cancer cells." (PMID 36623729, 2023). "The restoration of SLMAP-L or CETN3-S but not SLMAP-S and CETN3-L, efficiently reversed the effects of SRSF2 knockdown on the proliferation of colon cancer cells." (PMID 36623729, 2023). "Here, we demonstrated that SRSF2 controls many AS events by modulating both exon activation and repression in colon cancer cells through RNA-seq analysis and RT-PCR validation." (PMID 36623729, 2023). "To investigate whether SRSF2 played vital roles in human colon cancer cells, we first examined the expression levels of SRSF2 in CRC cell lines and normal colon cells." (PMID 36623729, 2023). "Both in vitro and in vivo, SRSF2 significantly accelerated the proliferation of colon cancer cells." (PMID 36623729, 2023). "In summary, the restoration of SLMAP-L or CETN3-S splice isoform could reverse the suppressions of proliferation affected by SRSF2 knockdown by mediating the cell cycle progression in colon cancer cells." (PMID 36623729, 2023). "To identify the roles these validated AS events played in colon cancer cells and whether they were mediated by SRSF2, we first designed the specific shRNAs targeting the validated splice variants and detected the roles they played in vitro." (PMID 36623729, 2023). "We next decided to investigate whether SLMAP-L or CETN3-S splice isoform mediates the effects of SRSF2 on the proliferation of colon cancer cells." (PMID 36623729, 2023). "Moreover, a significant reduction of the known cell proliferating marker 5-ethynyl-2′-deoxyuridine (EdU) was observed in both colon cancer cells’ knockdown of SRSF2 in comparison with the control cells." (PMID 36623729, 2023). "Rescue of SLMAP-L or CETN3-S splice isoform in SRSF2 knockdown colon cancer cells could effectively reverse the inhibition of cell proliferation by SRSF2 knockdown through mediating cell cycle progression." (PMID 36623729, 2023). "However, it remains unclear whether SRSF2 promotes proliferation of colon cancer cells via mediating cell cycle." (PMID 36623729, 2023). "Strikingly, SRSF2 knockdown also induced severe inhibition of colony formation of both RKO and HT29 colon cancer cells in vitro." (PMID 36623729, 2023). "Our data identified that SRSF2 was highly expressed in CRC tumors and promoted the proliferation of colon cancer cells in vitro and in vivo." (PMID 36623729, 2023).
HIV-1 infection (6 papers, 2008 to 2026). The type species of lentivirus and the etiologic agent of acquired immunodeficiency syndrome (AIDS). "In the first week following HIV-1 infection, the SRSF2 expression was significantly increased in H9 cells and MDMs." (PMID 38932230, 2024). "HIV-1 infection in macrophages per se might affect the nuclear import/export pathways used by SRSF2, such as the transporting SR system, or alternatively by the reversible phosphorylation of the RS domain that regulates the subcellular localization and shuttling of SR proteins." (PMID 38932230, 2024). "Moreover, HIV-1 infection in MDMs resulted in elevated expression of SRSF2, which might in turn facilitate HIV-1 transcription by elevating tat mRNA." (PMID 38932230, 2024).
renal carcinoma (6 papers, 2016 to 2022). A carcinoma arising from the epithelium of the renal parenchyma or the renal pelvis. "The inhibition of apoptosis pathways through decreased expression of SRSF2 in renal cancers was also reported." (PMID 35326115, 2022). "In clear cell renal cell carcinomas, SRSF2 is commonly decreased and knockdown of SRSF2 in renal cancer-derived cell lines results in decreased expression of MCL1S isoforms and inhibiting the apoptotic pathways." (PMID 29361709, 2018). "Altogether, these results showed that decreased SRSF2 expression protects viability of renal cancer cells." (PMID 27690003, 2016). "To see if SRSF2 affects spontaneous apoptosis in renal cancer cells, we silenced SRSF2 in the Caki-2 cell line and analysed populations of apoptotic cells using annexin V/propidium iodide (PI) staining." (PMID 27690003, 2016). "RNA from Caki-2 cells with silenced SRSF2 expression was subjected to the array analysis and the results were independently validated on three additional renal cancer-derived cell lines (UOK171, KIJ-265T, and KIJ-308T)." (PMID 27690003, 2016). "Silencing of SRSF2 in the four renal cancer-derived cell lines resulted in concomitant changes of splicing profile of eight out of the 14 analysed genes." (PMID 27690003, 2016).
bladder cancer (5 papers, 2014 to 2025). "Furthermore, low expression levels of LOXL4 and SRSF2 – genes regulated by miR-29b-3p and miR-193a-3p – have been associated with inhibited apoptosis and enhanced multi-drug resistance in bladder cancer." (PMID 40061896, 2025). "The effect of SRSF2 on exon 5 splicing was further confirmed in three additional bladder cancer cell lines—HT-1376, SW-780, and HTB-9." (PMID 33753867, 2021). "The mechanism by which miR-193a-3p enhanced drug resistance was shown to be the inhibition of Serine/arginine-rich splicing factor 2 (SRSF2) and lysyl oxidase-like 4 (LOXL4) expression in bladder cancer cells." (PMID 36685879, 2022).
chronic lymphocytic leukemia (5 papers, 2015 to 2023). "In oncohematology, numerous spliceosome gene mutations have been identified in chronic lymphocytic leukemia (CLL), myelodysplastic syndromes, and lymphomas; among the most well-known of these are those involving SF3B1, U2AF1, and SRSF2." (PMID 26937306, 2015).
leukocytosis (5 papers, 2021 to 2026). "Accordingly, CMML patient harboring CSF3R T618I mutation had a myeloproliferative phenotype with leukocytosis but showed concomitant dysplastic features, probably derived from the presence of double splicing-factor mutations, SRSF2 P95L and SF3B1 K666N." (PMID 39907800, 2025). "Leukocytosis at diagnosis, complex karyotype, and mutations of IDH1 and SRSF2 were correlated with lower survival in the univariable analysis." (PMID 42125699, 2026). "The proportion of patients with leukocytosis > 13 G/L was significantly higher in SRSF2-mutated patients in the cBioPortal cohort but not in the ABCMML cohort." (PMID 40549056, 2025).
non-small cell lung carcinoma (5 papers, 2012 to 2024). A group of at least three distinct histological types of lung cancer, including non-small cell squamous cell carcinoma, adenocarcinoma, and large cell carcinoma. "Positive results were further validated by specific quantitative RT-PCR in both H358 cells and human non-small cell lung carcinoma (NSCLC) samples that we previously showed to over-express the SRSF2 protein." (PMID 24428911, 2014). "Immunohistochemical analysis of SRSF1 and SRSF2 proteins expression in non-small cell lung cancer according to histological subtype." (PMID 23071587, 2012). "In another study, mAb SC35 has been used as a reporter for phosphorylated SRSF2 in immunohistochemical analysis of tissue samples obtained from patients with Non Small Cell Lung Carcinoma, and was reported to be upregulated in cancer tissues compared to normal tissues." (PMID 33095160, 2020).
glioblastoma (4 papers, 2020 to 2022). The most malignant astrocytic tumor (WHO grade IV). "Driver mutations have been found in several RNA-binding proteins (e.g., SF3B1, U2AF1, SRSF2, HNRNPA2B1, SRRM2) in cancers ranging from blood malignancies to glioblastoma, but several questions remain regarding how widely this group of proteins and their targets are involved in cancer." (PMID 35581644, 2022).
liver cancer (4 papers, 2020 to 2024). An epithelial or non-epithelial malignant neoplasm that arises from the liver. "In addition, upregulation of typical splicing proteins such as SRSF2, hnRNPL, hnRNPA2, hnRNPA2B1 and hnRNPAB were previously observed in liver cancers 33-37, although their misregulated splicing events have not been fully identified." (PMID 32483414, 2020).
ovarian carcinoma (4 papers, 2018 to 2026). A malignant neoplasm originating from the surface ovarian epithelium. "Since SRSF2 is often overexpressed in ovarian cancer and mutated in PT-treated ovarian cancer, we have focused on the interaction between SFPQ, p54nrb, and SRSF2." (PMID 32332923, 2020). "We have previously reported a role for the splicing factor SRSF2 in the regulation of PT-induced alternative splicing in ovarian cancer and other groups also supported this possibility." (PMID 32332923, 2020). "In epithelial ovarian cancer cells, the SFPQ/SRSF2 pathway has been shown to play a key role in regulating chemotherapy-induced apoptosis." (PMID 35707369, 2022). "Our data demonstrate that the expression levels of SRSF2, SFPQ or p54nrb impact on the sensitivity of ovarian cancer cells to PT-induced death and support the possibility that targeting alternative splicing, could also represent a promising therapeutic option to overcome PT resistance." (PMID 32332923, 2020).
acute leukemia (3 papers, 2019 to 2026). A clonal (malignant) hematopoietic disorder with an acute onset, affecting the bone marrow and the peripheral blood. "Co-mutations varied by subtype; MDS/MPN, NOS, and CMML cases frequently harbored mutations in epigenetic regulators (ASXL1, TET2) and splicing factors (SF3B1, SRSF2, ZRSR2), while acute leukemia cases showed alterations in JAK3, STAT3, and NRAS." (PMID 40806796, 2025).
lung adenocarcinoma (3 papers, 2012 to 2017). A carcinoma that arises from the lung and is characterized by the presence of malignant glandular epithelial cells. "In this study, by using immunohistochemistry, we demonstrate that the SR proteins SRSF1 and SRSF2 are overexpressed in 63% and 65% of lung adenocarcinoma (ADC) as well as in 68% and 91% of squamous cell lung carcinoma (SCC), respectively, compared to normal lung epithelial cells." (PMID 23071587, 2012). "SRSF2 and phosphorylated SRSF2 were reported to correlate with aggressive features of lung adenocarcinoma but not with lung squamous cell carcinoma patients." (PMID 28253859, 2017).
mastocytosis (3 papers, 2015 to 2017). A clonal myeloproliferative neoplasm characterized by the proliferation and accumulation of neoplastic mast cells in one or multiple organs or organ systems. "The frequency of SRSF2 (23.6%) mutations in patients with mastocytosis appeared to be greater than TET2 mutations, at least in these studies." (PMID 26158763, 2015).
myeloid leukemia (3 papers, 2019 to 2020). A clonal proliferation of myeloid cells and their precursors in the bone marrow, peripheral blood, and spleen. "In vivo treatment of E7107 in SRSF2 mutated murine myeloid leukemia cells resulted in preferential cell death of cells harboring mutant SRSF2." (PMID 33333932, 2020). "We established the human myeloid leukemia K562 cell lines that stably expressed myc-tagged wild-type or mutant SRSF2 proteins, and then performed RNA-sequence to analyze the splicing pattern of each cell line." (PMID 31040863, 2019).